MIR302E (microRNA 302e)
Synonyms: hsa-mir-302e; MIRN302E
Gene: MicroRNA gene on chromosome 11 (7,234,766 to 7,234,837, forward strand). Ensembl gene ENSG00000221703.
Homologues: Orthologues: chimpanzee ptr-mir-302e (100% identical).